CXCR2 (C-X-C motif chemokine receptor 2)
Diseases named in the same sentence as CXCR2 in open-access papers (continued):
Sharing a sentence is not in itself a finding about the gene and the disease.
tumor (continued). "In the present study, we demonstrated that activated CXCR2 on HSPCs contributes to mo-MDSCs generation under tumor conditions." (PMID 31395859, 2019). "Patients whose tumours exhibited this stromal phenotype had poor prognosis and were more likely to have infiltration of myeloid-cells including CXCR2-positive cells." (PMID 31591445, 2019). "We observed similar findings with the 4T1-Luc as with the Cl66-Luc cells suggesting that once tumor cells are in the bloodstream, it is the Cxcr2 status of the host which determines their localization in the body." (PMID 30871004, 2019). "We also observed reduced tumor-induced osteolysis and osteoclast activation in the presence of CXCR2 knockdown Cl66 tumor cells in comparison with the Cl66-Control cells." (PMID 30871004, 2019). "Experimental murine studies and clinical correlation analyses have identified ligands for CXCR2 as major drivers of TAN recruitment into tumor lesions, involving CXCL1/KC, CXCL2/MIP-2, CXCL5/LIX, CXCL6, and MIF." (PMID 31293583, 2019). "Treatment with a CXCR2 inhibitor after tumor cell inoculation dramatically decreased the number of MDSCs in lymph nodes, suggesting the importance of the chemokine/CXCR2 signaling axis in MDSC recruitment." (PMID 31390756, 2019). "CXCR2 is expressed by many tumor cells and is involved in the chemotherapy resistance in different preclinical models of cancer." (PMID 30894861, 2019). "In the Kras mouse model, pancreas-specific inactivation of CXCR2 prevented OIS, correlating with increased tumor proliferation and decreased survival thus challenging the role of blocking CXCR2 to increase anti-tumor therapy." (PMID 31561620, 2019). "In tumor-bearing mouse models, targeting CXCR2-mediated TAN mobilization has been reported to increase the number of tumor-infiltrating lymphocytes and potentiate anti-programmed death 1 checkpoint blockade." (PMID 30691207, 2019). "We have previously shown that TAN in this MOPC tumor model express high amounts of CXCR2 on their surface." (PMID 31293583, 2019). "The mobilization of neutrophils to the tumor sites also requires an interplay between CXCR2 and its ligands CXCL1-3 and CXCL5-8." (PMID 31010242, 2019). "Accordingly, upregulation of CXCR2 has been also reported in PDAC KRAS-driven models, as well as the efficacy of blocking CXCR2 to restrain tumor growth." (PMID 31847096, 2019). "Combination of a CXCR2 antagonist and oxaliplatin was reported to result in a great decrease of tumor growth and angiogenesis in xenograft models." (PMID 30691207, 2019). "The suppression of CXCR2 expression limits tumor spheroid formation and aldefluor-positive rate in breast cancer cells, and increases the efficacy of anti-HER2 therapy in HER2-positive patients." (PMID 31788042, 2019). "In this study, we investigated the role of both tumor and host CXCR2 expression in tumor-induced osteolysis using syngenic mouse models." (PMID 30871004, 2019). "We observed a significant reduction in tumor-induced osteolysis and osteoclast homing at the tumor-bone interface in mice injected with Cl66 CXCR2 knockdown (Cl66-shCXCR2) cells in comparison with mice injected with Cl66-Control cells (Cl66-Control)." (PMID 30871004, 2019). "Here, CXCR2 expression on granulocyte and macrophage progenitor cells (GMPs) was found to participate in myeloid cell differentiation within the tumor environment." (PMID 31395859, 2019). "Consistent with observations in primary tumors, in most experiments CXCR2 blockade retained its inhibitory activity on the recruitment of peri-TAN by 3 days post injection also for the 2nd challenge tumor." (PMID 31293583, 2019). "IL-33 also triggers CXCR2 upregulation in tumor cell surface through a dysfunctional angiogenesis leading to ROS production." (PMID 31024531, 2019). "A recent study in pancreatic ductal adenocarcinomas demonstrated that inhibition of CXCR2 predominantly in neutrophils/MDSCs confers T cell entry to the tumor site." (PMID 31788042, 2019).
tumor (continued). "In this tumor, CXCR2 blockade still effectively inhibited the immediate recruitment of TAN into the tumor lesion at 2–3 h post injection." (PMID 31293583, 2019). "Taken together, our data demonstrate that patients' NK cells exhibit reduced surface expression of CXCR2, responsible for tumor trafficking." (PMID 31024520, 2019). "In PDAC, the CXCR2 axis is involved in MDSCs recruitment, angiogenesis, tumor cell proliferation, and migration." (PMID 30832219, 2019). "Similar to our finding in tumor-derived CXCR2, we observed a significant decrease in tumor growth and osteolysis in tumors formed by Cl66-Luc cells injected in Cxcr2−/− mice in comparison with Cl66-Luc cells injected in the wild type mice." (PMID 30871004, 2019). "CXCR2 neutralizing antibody also removed the survival benefit of sarcosine-treated DCs in the tumor models." (PMID 31753028, 2019). "Our findings reveal a critical role for CXCR2 in regulating hematopoietic progenitor cell differentiation under tumor conditions, and SAP18 is a key negative regulator in this process." (PMID 31395859, 2019). "In our study, immunostaining showed that the tumor cell inoculation increased CXCR2 expression in vlPAG neurons." (PMID 30606213, 2019). "Our result suggests that host CXCR2 positively influences tumor cell growth in the bone microenvironment." (PMID 30871004, 2019). "Recent studies indicated that infiltration of neutrophils and myeloid-derived suppressor cells (MDSCs) through the CXC ligands (CXCLs)–CXCR2 signaling also contribute to tumor progression in various cancers including PDAC16,17." (PMID 30659170, 2019). "Inhibiting CXCR2 in the genetically engineered PDAC mouse model that carried the oncogenic Kras mutation the and TGF-β receptor knockout disrupted the tumor-stromal interactions and improved mice survival." (PMID 30832219, 2019). "Upon research on diverse tumor models, it has been revealed that CXCR2 is a pressing chemokine receptor which recruits neutrophils to the tumor." (PMID 31474975, 2019). "Although the detailed mechanism behind decreased M2-like TAMs and increased M1-like TAMs in PKF2h mice remains to be elucidated, increase of M1/M2 ratio by Cxcr2 inhibition would be effective for modulating the immune tumor microenvironment of PDAC." (PMID 30659170, 2019). "Inhibition of CXCR2 signaling has been shown to disrupt tumor-stromal interactions and improves survival in murine PDA models." (PMID 31652904, 2019). "Lastly, to evaluate tumor CXCR2 signaling, we analyzed osteoclast homing at the tumor-bone interface in the sections of mice injected with Cl66-Control or Cl66-shCXCR2 cells." (PMID 30871004, 2019). "All A20-28z CXCR2+ CAR T-cell treated mice had stable low burden tumor at the experimental endpoint." (PMID 31091832, 2019). "In murine tumor models CXCR2 blockade has been shown to modulate neutrophil trafficking to sites of chronic inflammation, subsequently reduced tumor and metastasis formation and enhanced treatment efficacy in distinct therapeutic conditions." (PMID 31293583, 2019). "In contrast, only one of three mice treated with A20-28z CAR T-cells that lack CXCR2 showed an anti-tumor response with the remainder developing progressive disease, comparable to that seen in control mice." (PMID 31091832, 2019). "Nevertheless, the relevant mechanism by which CXCR2 regulates mo-MDSCs accumulation in the tumor microenvironment remains unexplored." (PMID 31395859, 2019). "For example, in an inflammatory colitis and colon cancer model, CXCR2 null mice were protected against development of disease, with tumor progression restored only after adoptive transfer of activated MDSCs." (PMID 30081463, 2018). "Here we explore the role of the CXCR2 pathway on PMN-MDSCs in the tumor microenvironment and the mechanisms of CXCR2-driven enhancement of checkpoint blockade." (PMID 30400822, 2018).
tumor (continued). "Within the tumor microenvironment, platelets secrete CXCL5 and CXCL7, as a consequence of direct contact with tumor cells or following activation of the coagulation cascade, thus supporting the recruitment of CXCR2-positive myeloid cells." (PMID 30591657, 2018). "In conclusion, Snail upregulates the expression of CXCL1/2 and enhance MDSC tumor infiltration via CXCR2; MDSCs were shown to inhibit anti-tumor immunity and promote tumor progression." (PMID 29703902, 2018). "Since Cxcl1 exhibited the greatest change in expression among all chemokine genes after Plac1 downregulation, mice were treated with a Cxcr2 antagonist to determine if it would affect tumor growth to a similar extent." (PMID 29632317, 2018). "Neutrophils expressing CXCR1 and CXCR2 are attracted to the tumor site following a gradient of concentration of CXCL8 secreted by tumor cells." (PMID 29977225, 2018). "Gal‐3 overexpression in RCC promoted both in vitro and in vivo tumorigenicity, and its expression was correlated with CXCR2 expression and tumour progression in clinical tissues." (PMID 30246456, 2018). "KEGG signaling pathways analysis on these DE genes showed their involvement in several critical pathways associated with tumor progression, including pathways in cancer, PI3K/AKT, IL-8/CXCR2, ERK/MAPK, apoptosis, and HIF-1 signaling pathways." (PMID 30173296, 2018). "Anti-tumor activity was assessed in the B16-F10 syngeneic tumor model utilizing a small molecule antagonist of CXCR2, MK-7123 (Navarixin) and an anti-mouse PD-1 blocking antibody, muDX400." (PMID 30400822, 2018). "CXCR2+neutrophils were identified as brown-stained segmented cells that surrounded the tumour cells." (PMID 29661142, 2018). "Its essential role in influencing tumour microenvironment makes CXCR2 an important target for anti-tumour metastasis treatment." (PMID 30109074, 2018). "While targeting CXCR2 alone only modestly decreased tumor burden in a murine RCC model, combination with immune checkpoint inhibition significantly reduced tumor weight." (PMID 30319622, 2018). "CXCL5 is a chemokine that can recruit neutrophils and CXCR2+ myeloid cells, including myeloid-derived suppressor cells (MDSCs) and monocytes that can be a precursor of TAMs in tumor-bearing hosts." (PMID 29643991, 2018). "CXCR-2 in a cell type-specific manner can act both as a tumor suppressor where it induces senescence in premalignant lesions of PDAC and as tumor promoting via enhancing neutrophil and MDSC recruitment to TME." (PMID 30158932, 2018). "CXCL5 can bind CXCR2 to mediate various cellular behaviours that include neutrophil recruitment and tumour cell migration and invasion." (PMID 29665837, 2018). "Our studies have demonstrated that anti-PD-1 antibody immunotherapy promotes the recruitment of granulocytic myeloid-derived suppressor cells (Gr-MDSCs) to the tumor bed in a CXCR2-dependent manner." (PMID 30400822, 2018). "We have shown that oxysterols released from tumor cells recruit neutrophils endowed with pro-angiogenic and immunosuppressive abilities through a mechanism requiring the CXCR2 chemokine receptor and independently of LXRs." (PMID 30333826, 2018). "Recently, mouse Cxcr2 was demonstrated to play a role in neutrophil accumulation within the tumor as well as T cell infiltration and tumor metastasis." (PMID 30185911, 2018). "Gal‐3 and CXCR2 expressions were correlated with RCC tumour progression, and Gal‐3 expression correlated with CXCR2 expression in RCC tissues." (PMID 30246456, 2018). "We demonstrated that the CXCR2 antagonist SB265610 suppresses the recruitment of G-MDSCs to the tumor and thereby inhibits tumor progression." (PMID 29703902, 2018). "Inhibition of CXCL8–CXCR1/2 signaling by CXCL8 antibodies, or small molecules targeting CXCR1 and/or CXCR2, also decreases tumor growth and progression in tumor mouse models." (PMID 30304046, 2018).
tumor (continued). "Granulocytic MDSCs, mainly composed by different subsets of neutrophils, express CXCR1 and CXCR2, and are recruited to the tumor by CXCL8, produced by tumor cells or by Treg." (PMID 30319638, 2018). "FOXC1 is also associated with the IL-8 signaling pathway and the transactivation of genes responsible for tumour angiogenesis and metastasis, CXCR2 and CCL2." (PMID 29487724, 2018). "It is also reported that introduction of CXCR2 in tumor antigen specific CD8+ T cells enhances their infiltration into the tumor that expresses the ligand CXCL1 and thereby reduces tumor growth in a mouse model of colon cancer." (PMID 30483271, 2018). "Using Cox survival analysis, we found that patients with higher co‐expressions of Gal‐3 and CXCR2 had a significantly worse survival rate and that Gal‐3 expression correlated with CXCR2 expression, tumour progression and prognosis in RCC." (PMID 30246456, 2018). "CXCL1 is upregulated in various cancers and associated with cancer progression, such as cancer cell growth, proliferation, tumor angiogenesis and metastasis, after the activation of CXCR2." (PMID 30115896, 2018). "The pro-inflammatory CXC cytokine interleukin 8 (IL-8), secreted by tumour cells and tumour-associated macrophages (TAMs), are critical factors that bind to the receptors CXCR1 and CXCR2 to promote tumour angiogenesis and metastasis." (PMID 29487724, 2018). "The concomitant expression of CXCL5 and CXCR2 makes a substantial contribution to the tumour progression of NPCs." (PMID 29665837, 2018). "Studies have shown that stimulating the neutrophil surface of CXCR1 can lead to neutrophil chemotaxis and activation, and inhibition of CXCR1 and CXCR2 can reduce the migration of neutrophils to tumor regions." (PMID 30123110, 2018). "In mouse tumor models, CXCR2 blockade disrupts the trafficking of CD11b(+)Ly6C(-)Ly6G(+) PMN-MDSCs/neutrophils in the tumor microenvironment and enhances the anti-tumor effect of checkpoint blockade." (PMID 30400822, 2018). "First, 4T1 cells co-cultured with CXCR2+ MDSCs sorted from spleen of tumor-bearing mice displayed mesenchymal-like morphology in vitro." (PMID 29383101, 2017). "Previous studies demonstrated that different CXCR1 and CXCR2 antagonists can block these receptors inhibiting inflammation and tumor growth in various animal models." (PMID 28129639, 2017). "CD4+ or CD8+ T cells were cultured with or without Ly6G+CXCR2− cells sorted from spleen of normal mice or CXCR2+ MDSCs sorted from spleen of 4T1 tumor-bearing mice under the stimulation of anti-CD3 and anti-CD28 for 3 days." (PMID 29383101, 2017). "All three have been implicated in tumor proliferation, angiogenesis, and metastasis via activation of multiple upstream pathways, including STAT3, CXCR1 and CXCR2, and NF-κB, respectively." (PMID 27525640, 2017). "Its function in inflammation and tumor-related inflammatory activities is vital and CXCR2 modulation has been suggested for treatment." (PMID 28769990, 2017). "Consistently, results from validation set also revealed the correlation between high expression of CXCR2 and Dukes stage (P = 0.018), tumor invasion (P = 0.018) and liver metastasis (P = 0.047)." (PMID 28415702, 2017). "We next examined the expression of Cxcl5, Ppbp, and their cognate receptor genes, Cxcr1 and Cxcr2 in tumor cells and metastasis target organs of our models." (PMID 28341702, 2017). "We provided strong evidence that CXCR2 overexpression in tumor tissue was an independent predictor of poor OS, RFS, and DFS in most cancers regardless of the ethnic background of patients in this meta-analysis." (PMID 29312644, 2017). "It has been reported that IL-17a can induce CXCL5 production by liver tumor cells and enhance infiltration of MDSCs into tumor sites in a CXCL5/CXCR2 dependent manner." (PMID 29383101, 2017).
tumor (continued). "Immunofluorescence was performed to further verify the location of CXCR2 and tumor mesenchyme was counterstained by α-SMA." (PMID 28415702, 2017). "While NGFR-transduced cells did not respond to CXCL8, they released calcium upon stimulation with tumor supernatants, albeit 2 to 6 times less than CXCR2-transduced NK cells." (PMID 28923105, 2017). "Schwertfeger and colleagues showed that macrophages are recruited to mammary hyperplasias in response to FGFR activation, where they promote tumor cell migration and invasion in a CXCR2-dependent manner." (PMID 28881599, 2017). "All studies were published in 2010 or later and assessed CXCR2 expression in tumor tissue by immunohistochemistry." (PMID 29312644, 2017). "For the calcium flux assay, NK cells transduced with CXCR2 or the control NGFR were stimulated with recombinant CXCL8 or conditioned RCC tumor supernatants." (PMID 28923105, 2017). "In this study, we show that genetic modification of human NK cells to re-express the chemokine receptor CXCR2 conferred the ability to specifically migrate to RCC tumor-derived CXCR2 ligands resulting in increased killing of target cells." (PMID 28923105, 2017). "Genetic modification of human primary NK cells to re-express CXCR2 improved their ability to specifically migrate along a chemokine gradient of recombinant CXCR2 ligands or RCC tumor supernatants compared with controls." (PMID 28923105, 2017). "CXCR2 is a member of the G-protein-coupled receptor superfamily and a number of studies have demonstrated that CXCR2 plays a pivotal role in tumor angiogenesis, proliferation and invasion." (PMID 28415702, 2017). "We next measured whole tumor RNA levels of the chemokine receptors CXCR2 and CSF1R as well as the cognate chemokines for these receptors, CXCL1/CXCL2 and CSF1, respectively." (PMID 28915554, 2017). "The up-regulation of the IL-8 receptors CXCR1 and CXCR2 is a frequent occurrence in human cancer and has been related to tumor progression." (PMID 28415590, 2017). "We show here that genetic modification of human primary NK cells to re-express CXCR2 improves their ability to specifically migrate along a tumor-derived chemokine gradient resulting in increased killing of target cells." (PMID 28923105, 2017). "CXCR2 plays an important role on tumor progression in several types of cancer such as prostate cancer, gastric cancer and lung cancer." (PMID 28415702, 2017). "The CXCR2 is induced by mutated KRAS in pancreatic cancer cells and is required for autocrine growth of tumor cells and for inhibition of oncogene-induced senescence." (PMID 29156578, 2017). "This cytokine is able to initiate multiple signaling pathways by activating two cell surface G-protein coupled receptors, CXCR1 and CXCR2, resulting in angiogenesis, tumor metastasis and tumorigenesis." (PMID 28881741, 2017). "One pioneer study demonstrated that blocking CXCR2 disrupted PMN-MDSC trafficking to tumor sites and sensitized the tumors to anti-PD-1 treatment in mice;7 however, this approach specifically targeted PMN-MDSCs but not M-MDSCs and TAMs." (PMID 28894087, 2017). "Tumor progression depends on adequate blood supply, and there is evidence that CXCR2 is essential for tumor angiogenesis." (PMID 29312644, 2017). "CXCR2 signaling is known to contribute to tumor progression in various cancers by promoting tumor cell growth, angiogenesis and infiltration of immunosuppressive cells in the tumor microenvironment." (PMID 26771140, 2016). "When gene-engineered to express CXCR2, T cells displayed enhanced trafficking towards tumor cells secreting the corresponding chemokine CXCL1." (PMID 27096098, 2016). "Consistent with our results, silencing CXCR2 inhibited subcutaneous tumor formation in nude mice injected with SKOV-3 cells." (PMID 27723802, 2016). "Acquisition of IL-8 and/or its receptors CXCR1 and CXCR2 are known to be a relatively common occurrence during tumor progression." (PMID 27348007, 2016).